PEX3 (peroxisomal biogenesis factor 3)
Diseases named in the same sentence as PEX3 in open-access papers:
PEX3 is named in the same sentence as 35 diseases in open-access papers, as found by Europe PMC text mining. Sharing a sentence is not in itself a finding about the gene and the disease. The quoted sentences say what the papers report.
Zellweger syndrome (9 papers, 2011 to 2025). "The human orthologs of PEX19 and PEX3, together with other peroxins, are mutated in Zellweger syndrome, a severe cerebro‐hepato‐renal peroxisome biogenesis disorder (Fujiki, Yagita, & Matsuzaki, 2012)." (PMID 31854076, 2020). "Namely, PEX3 mutations are related to Zellweger syndrome (ZWS), a neurologic dysfunction with craniofacial abnormalities and liver dysfunction." (PMID 30622661, 2018). "As observed in S. cerevisiae cells, human Pex3 fused to a signal peptide can complement Zellweger syndrome fibroblasts deficient in Pex3." (PMID 25681696, 2015). "Finally, the proteomic approach led to some interesting insights with potential medical relevance, for example, a link between PEX3, associated with Zellweger syndrome, and the biogenesis of various collagens." (PMID 41009394, 2025). "Moreover, PEX13 also displayed profuse mitochondria localization in PEX3-deficient human fibroblasts derived from Zellweger syndrome patients." (PMID 38088545, 2024). "For TRAP and PEX3, fibroblasts from patients with Congenital Disorders of Glycosylation and Zellweger Syndrome patients, respectively, were analyzed in parallel with control fibroblasts." (PMID 41009394, 2025). "This problem originally also occurred after transient depletion of PEX3, Sec62, and Sec63 and was the reason for the use of CRISPR/Cas9-mediated Sec62- as well as Sec63-knock-out cells or fibroblasts from PEX3-deficient Zellweger Syndrome patients." (PMID 41009394, 2025). "Here, we developed potential Drosophila models for Zellweger syndrome, in which the Drosophila pex3 or pex16 gene was disrupted." (PMID 21826223, 2011). "The human peroxin genes PEX3 or PEX16 are required for peroxisomal membrane protein targeting, and their mutations cause Zellweger syndrome, a class of PBDs." (PMID 21826223, 2011). "Indeed, mutations in the PEX3 and the PEX19 genes lead to the most severe form of the peroxisomal biogenesis disorders, the Zellweger syndrome." (PMID 28817674, 2017). "Loss of function mutations in Pex3 result in a complete absence of peroxisomal structures and in humans this leads to the lethal Zellweger syndrome." (PMID 23951409, 2013). "Zellweger spectrum disorders (ZSDs), including archetypal Zellweger syndrome, neonatal adrenoleukodystrophy (NALD) and infantile Refsum disease (IRD), are PBDs caused by mutations in peroxin genes (PEX1, PEX2, PEX3, PEX5, PEX6, PEX10, PEX11β, PEX12, PEX13, PEX14, PEX16, PEX19 or PEX26)." (PMID 40949164, 2025). "For this reason, organs and cell types containing high amounts of PEX3 and PEX19 could be more frequently negatively affected by defects of the peroxisomal biogenesis such as occur in diseases of the Zellweger syndrome spectrum and neonatal adrenoleukodystrophy." (PMID 28817674, 2017).
melanoma (7 papers, 2018 to 2023). A malignant, usually aggressive tumor composed of atypical, neoplastic melanocytes. "We chose genetic inhibition of PEX3 as a mode to disrupt peroxisome biogenesis in a panel of melanoma cells harboring different genetic driver mutations." (PMID 37616051, 2023). "Similar to our human melanoma cell data, the D4M.3a Pex3+/– clones were more susceptible to MAPKi-mediated cell death than their Cas9-Ctrl counterparts." (PMID 37616051, 2023). "Recently, three ARGs including WIPI1, BAG1 and PEX3 were found to be melanoma diagnostic biomarkers with high AUC values, sensibility and specificity values." (PMID 32003756, 2020). "To formally test the impact of disrupting peroxisome biogenesis on response to MAPKis, we knocked down PEX3 with siRNAs in 4 human melanoma cell lines harboring different genetic mutations to assess whether this would alter their response to MAPK inhibition." (PMID 37616051, 2023). "Lipidomic analyses of Pex3+/– D4M.3a melanoma cells reveal altered levels of ceramide-derived lipid species and increased metabolic vulnerability." (PMID 37616051, 2023). "The increased treatment benefit in mice bearing Pex3+/– melanomas was recapitulated in a separate cohort of mice that were administered PLX4720 chow when their tumors reached 800 mm3 in size." (PMID 37616051, 2023). "PEX3 knockdown sensitized all melanoma subtypes to MAPKi-induced apoptosis, compared with the same cells transfected with scrambled siRNA control (siCtrl)." (PMID 37616051, 2023). "Increased levels of peroxisomal genes and UGCG were found in patient-derived MAPKi-relapsed melanomas, and simultaneously inhibiting PEX3 and UGCG restored MAPKi sensitivity in multiple models of therapy resistance." (PMID 37616051, 2023). "To test the sensitivity of Pex3+/– melanomas to BRAF inhibition in vivo, we next injected D4M.3a Cas9-Ctrl, Pex3+/– clone 6D, or Pex3+/– clone 9G cells into syngeneic mice." (PMID 37616051, 2023). "Knockdown of PEX3 significantly decreased the number of peroxisomes in all 4 melanoma cell lines, with minimal impact on cell viability." (PMID 37616051, 2023). "In this present study, we showed that compromising peroxisome biogenesis by targeting PEX3 (or PEX19) sensitizes melanoma to MAPK pathway inhibition and overcomes MAPKi resistance, a phenotype that is more robust when UGCG is simultaneously inhibited." (PMID 37616051, 2023). "To model our in vitro results in mice, we sought to knock out Pex3 in the BRAFV600E-mutant melanoma cell line D4M.3a." (PMID 37616051, 2023). "Reduced PEX3 expression in melanoma cells potentiated their response to MAPK inhibition in vitro and in vivo." (PMID 37616051, 2023). "To verify these results in human melanoma cells, we generated PEX3-knockout (PEX3-KO) A375M cells and similar data were obtained as in our murine models." (PMID 37616051, 2023). "The molecular mechanisms underlying the functional interaction of BAG1, PEX3, and WIPI1 with melanoma were investigated with Chilibot analysis." (PMID 30622661, 2018). "BAG1 and PEX3 expression was also found significantly reduced in metastatic vs primary melanoma (p = 0.00004 and p = 0.002, respectively), indicating their possible role in the metastatic dissemination phase." (PMID 30622661, 2018). "We conclude that WIPI1 (AUC = 0.99), BAG1 (AUC = 1), and PEX3 (AUC = 0.93) are relevant novel melanoma markers at both gene and protein levels." (PMID 30622661, 2018). "Noteworthily, BAG1, PEX3, and WIPI1 are all membrane-associated molecules and intracellular vesicles play a key role in melanoma biology." (PMID 30622661, 2018). "PEX3 knockdown combined with PPMP potentiated MAPKi-induced apoptosis in our melanoma cell lines." (PMID 37616051, 2023). "Once initiated, the Pex3+/– melanomas grew at a similar rate to that of the Cas9-Ctrl group." (PMID 37616051, 2023).
melanoma (continued). "However, 100% (7/7) of mice harboring PLX4720-resistant Pex3+/– melanomas had improved tumor control and significantly increased OS on the PPMP therapy." (PMID 37616051, 2023). "Cotargeting PEX3 and UGCG selectively eliminated a subset of metabolically active, drug-tolerant CD36+ melanoma persister cells, thereby sensitizing melanoma to MAPKis and delaying resistance." (PMID 37616051, 2023). "We here conclude that dual inhibition of PEX3 and UGCG has potential clinical benefit in MAPK-targeted therapy-resistant melanomas." (PMID 37616051, 2023). "Dual blockade of PEX3 and UGCG effectively eliminated CD36+ cells, leading to a dramatic induction of apoptosis in MAPKi-treated melanoma cells and improved response to MAPKi and PFS in our preclinical models." (PMID 37616051, 2023). "Cotargeting PEX3 and UGCG not only potentiated melanoma response to MAPK inhibition but also delayed the onset of resistance (i.e., prolonged PFS)." (PMID 37616051, 2023). "We next evaluated the efficacy of dual inhibition of PEX3 and UGCG in a panel of melanoma cell lines with acquired MAPKi resistance." (PMID 37616051, 2023). "According to Pubmed searches, ARSA, the arylsulfatase A gene, appears to mediate BAG1, PEX3, and WIPI1 interaction with melanoma." (PMID 30622661, 2018). "In conclusion, the present study highlights 3 genes (BAG1, PEX3, and WIPI1), known to play a key role in autophagy, as novel relevant melanoma markers." (PMID 30622661, 2018). "BAG1, CHMP2B, PEX3, and WIPI1 confirm strongly different expression levels in melanoma vs healthy skin in IST Online." (PMID 30622661, 2018). "BAG1, PEX3, and WIPI1 were identified as the best three novel candidates as validated markers in both DNA and protein melanoma samples, while CHMP2B has validated differential expression at the DNA level, not observed at the protein level." (PMID 30622661, 2018). "A second-round validation performed on the Human Protein Atlas database showed strong differential protein expression for BAG1, PEX3, and WIPI1 in melanoma vs control samples, according to the image analysis of 80 human histological sections." (PMID 30622661, 2018). "We conclude that BAG1, CHMP2B, PEX3, and WIPI1 show a strongly different expression in melanoma vs control biopsies, according to data from 418 patients, and have never been related to melanoma according to Pubmed." (PMID 30622661, 2018). "This subset of melanoma patients may have limited clinical response to MAPK-targeted therapy, which can potentially be improved by combined inhibition of PEX3 and UGCG." (PMID 37616051, 2023). "PEX3 expression shows no significant prognostic value in melanoma patients while it is a favorable prognostic marker in renal cancer patients (p < 0.0001)." (PMID 30622661, 2018). "Interestingly, ARSA (arylsulfatase A) is the only ARG mediating BAG1, PEX3, and WIPI1 relation with melanoma." (PMID 30622661, 2018). "We concluded that the role of BAG1, PEX3, and WIPI1 as potential melanoma markers is novel and their action on melanoma may occur at the intracellular vesicle level via molecular pathways involving other ARGs." (PMID 30622661, 2018). "Our data showed that cotargeting PEX3 and UGCG could (a) sensitize RAS-mutant and NF1-mutant melanoma cells to MEKi-induced apoptosis, (b) delay the onset of acquired resistance in vivo, and (c) restore drug sensitivity in resistant/relapsed melanomas." (PMID 37616051, 2023).
lymphoma (3 papers, 2020 to 2025). A malignant (clonal) proliferation of B- lymphocytes or T- lymphocytes which involves the lymph nodes, bone marrow and/or extranodal sites. "In a lymphoma model, it has been demonstrated that peroxisome biogenesis factors, such as PEX3, PEX16, and PEX19, contribute to tumorigenesis." (PMID 41373547, 2025). "Notably, silencing PEX3 to inhibit peroxisome function resulted in a 70% increase in cell death, suggesting that reducing peroxisome levels decreases the resistance of lymphoma cells to treatment." (PMID 41373547, 2025). "The depletion of PEX3 compromised peroxisome biogenesis in lymphoma cells." (PMID 32674458, 2020). "Moreover, PEX3 knockdown rendered lymphoma cells more prone to ROS-induced apoptosis." (PMID 32674458, 2020). "Another investigation uncovered that the proteins PEX3, PEX16, and PEX19 safeguard lymphoma cells by counteracting cell death prompted by the histone deacetylase inhibitor." (PMID 40487257, 2025).
male infertility (3 papers, 2022 to 2023). The inability of the male to effect fertilization of an ovum after a specified period of unprotected intercourse. "The inactivation of ether lipid biosynthesis has been shown to cause male infertility and eye abnormalities; both of these impairments were observed in Pex3-deficient mice." (PMID 36291074, 2022). "Hence, we conclude that YYH is able to exert antioxidant functions through a P16-dependent pathway to improve male infertility caused by Pex3-KO." (PMID 35058429, 2022). "We found that Pex3−/− mice had abnormal sperm, male infertility, and increased testicular ROS levels but that the overall functioning of their other organs was completely normal." (PMID 35058429, 2022). "Preliminary studies revealed that Pex3-KO led to dyszoospermia and male infertility in male mice, which suggested that the Pex3-KO mouse model was a good model with which to study the reproductive effects and mechanisms of antioxidants." (PMID 35058429, 2022).
ovarian carcinoma (2 papers, 2021). A malignant neoplasm originating from the surface ovarian epithelium. "HDAC1, PEX3, MTMR14, and RB1 had the moderate intensity and high quantity in ovarian cancer." (PMID 33748162, 2021).
peroxisomal disorders (2 papers, 2020 to 2023). "The increased PL and decreased EPL levels in Pex3+/– D4M.3a cells are consistent with clinical phenotypes detected in patients with peroxisomal disorders and corresponding PEX3 biallelic mutant cell lines in vitro." (PMID 37616051, 2023).
African sleeping sickness (1 paper, 2021). "Given the essentiality of functional glycosomes and the low amino acid sequence identity between TbPex3 and mammalian Pex3 proteins, makes TbPex3 and its interaction with Pex19 an attractive therapeutic target for the treatment of NTDs like African sleeping sickness and American trypanosomiasis." (PMID 34350186, 2021).
COVID-19 (1 paper, 2025). A disease caused by infection with severe acute respiratory syndrome coronavirus 2. "Suppressed PEX3, PMP70 and PEX14 immunolabeling in vitro.Suppressed PEX3, PEX11β, PEX5L and PEX14 mRNA levels and decreased PMP70 and PEX14 protein levels in brain tissue from COVID-19 patients versus controls.Suppressed Pex3 mRNA and catalase protein in brains from infected hamsters." (PMID 40949164, 2025).
Down syndrome (1 paper, 2024). "We report the finding of a cytogenetically balanced, de facto genomically unbalanced translocation that poses a challenge in a case of prenatal diagnosis, changing the risk of Down syndrome in a Zellweger syndromic spectrum risk (PEX3 deletion)." (PMID 39202220, 2024).
Hyperoxaluria (1 paper, 2024). Increased excretion of oxalates in the urine. "It has been associated with hyperoxaluria with NL and NC with variants in PEX1 and PEX3, likely with variants in PEX5, and possibly with variants in PEX6, PEX7, PEX10, PEX11, PEX12, PEX13, PEX16, and PEX26." (PMID 38606357, 2024). "It has been associated with hyperoxaluria with NL and NC with variants in PEX1, likely with variants in PEX5, and possibly with variants in PEX3, PEX6, PEX 10, PEX 12, PEX13, PEX14, PEX16, PEX19, and PEX26." (PMID 38606357, 2024).
metastatic melanoma (1 paper, 2018). A melanoma that has spread from its primary site to another anatomic site. "An additional way to evaluate the potential prognostic values of BAG1, PEX3, and WIPI1 was carried out by assessing their expression in primary vs metastatic melanoma samples." (PMID 30622661, 2018).
osteosarcoma (1 paper, 2025). A usually aggressive malignant bone-forming mesenchymal neoplasm, predominantly affecting adolescents and young adults. "In osteosarcoma, decreased NSUN6 expression reduced m5C modifications on PEX1 and PEX3 mRNA, leading to PEX1 and PEX3 instability by losing the binding of the m5C recognition protein YBX1." (PMID 41462962, 2025).
prostate carcinoma (1 paper, 2024). A carcinoma that arises from epithelial cells of the prostate gland. "PC3-LN4 prostate cancer cells lacking PIM1, which display higher GSK3β activation, show a significant decrease in genes linked to peroxisomal biogenesis (peroxisomal biogenesis factor 3 and 5; PEX3 and PEX5) and LD growth (Tip47)." (PMID 38097734, 2024).
trypanosomiases (1 paper, 2021). "Our results show that preferential disruption of trypanosomal Pex3 function by small molecule inhibitors could help in the accelerated development of drugs for the treatment of trypanosomiases." (PMID 34350186, 2021).
tuberous sclerosis (1 paper, 2017). Hereditary disease characterized by seizures, intellectual disability, developmental delay, and skin and ocular lesions. "It was recently shown that the overexpression of PEX3 induces ubiquitination-dependent NBR1-mediated pexophagy and that PEX19 associates with the tuberous sclerosis complex, which is part of the signaling cascade downstream of ATM activating pexophagy in the presence of ROS." (PMID 28817674, 2017).
virus infection (1 paper, 2019). "We demonstrate that Sgroppino localizes to peroxisomes and that knock-down of the peroxisome biogenesis factor Pex3 causes hypersensitivity to virus infection." (PMID 30765784, 2019). "In addition, knock-down of Pex3, an essential peroxisome biogenesis factor, increases sensitivity to virus infection." (PMID 30765784, 2019).
West syndrome (1 paper, 2024). "Among the responders with West syndrome, three out of four patients were identified, with mutations detected in EXOC8 and PEX3 genes." (PMID 39359873, 2024).
infection (4 papers, 2015 to 2022). The state of being infected such as from the introduction of a foreign agent such as serum, vaccine, antigenic substance or organism. "The loss of multiple PEX proteins was evident at 24-h post-infection; however, by 48-h, the reduction in PEX3, PEX7, PEX11B, PEX13 and PEX19 was much more pronounced." (PMID 31311201, 2019). "Importantly, both PEX3 and HPRT1 KD blocked HCMV at early stages of infection as the expression of early-proteins IE2 and UL44 was reduced." (PMID 26599541, 2015).
tumor (3 papers, 2021 to 2025). "Without PPMP treatment, all mice needed to be euthanized within 48–72 hours regardless of their Pex3 status due to their large tumor size." (PMID 37616051, 2023).
PEX3 also shares sentences with these, for which no sentence is quoted: colon cancer (2 papers); infertile (2); American trypanosomiasis (1); Breast Invasive Carcinoma (1); cancer (1); clear-cell renal cell carcinoma (1); congenital disorder of glycosylation (1); liver dysfunction (1); myocardial infarction (1); neurological diseases (1); periodontitis (1); peroxisome biogenesis disorder (1); renal carcinoma (1); Seckel syndrome (1); vitiligo (1); Zellweger spectrum disorders (1).